OXER1 (oxoeicosanoid receptor 1)
Description:
Receptor for eicosanoids and polyunsaturated fatty acids such as 5-oxo-6E,8Z,11Z,14Z-eicosatetraenoic acid (5-OXO-ETE), 5(S)- hydroperoxy-6E,8Z,11Z,14Z-eicosatetraenoic acid (5(S)-HPETE) and arachidonic acid. Seems to be coupled to the G(i)/G(o), families of heteromeric G proteins.
Synonyms: GPR170; TG1019; GPCR
Tractability: Small molecule: a high-quality ligand is known; it belongs to a druggable protein family. Antibody: its Gene Ontology location is reachable by antibodies, with high confidence; UniProt predicts a signal peptide or a membrane-spanning region. PROTAC: ubiquitination databases record sites on it; a small molecule that binds it is known.
Target class: Leukotriene receptor; Small molecule receptor (family A GPCR); Membrane receptor; Lipid-like ligand receptor (family A GPCR); Family A G protein-coupled receptor
Gene: Protein-coding gene on chromosome 2 (42,762,499 to 42,764,135, reverse strand). Ensembl gene ENSG00000162881.
Subcellular location: Membrane
Pathways (Reactome):
Signal Transduction: Eicosanoid ligand-binding receptors; G alpha (i) signalling events
Gene Ontology:
Molecular function: 5(S)-hydroxyperoxy-6E,8Z,11Z,14Z-icosatetraenoic acid binding; 5-hydroxy-6E,8Z,11Z,14Z-icosatetraenoic acid binding; 5-oxo-6E,8Z,11Z,14Z-icosatetraenoic acid binding; G protein-coupled receptor activity; protein binding
Biological process: adenylate cyclase-inhibiting G protein-coupled receptor signaling pathway; G protein-coupled receptor signaling pathway
Cellular component: plasma membrane; membrane
Genetic constraint (gnomAD): Loss-of-function variants: 1 observed, 0.74 expected, observed/expected ratio (o/e) 1.34, 90% interval 0.3 to 1.91. That is too few expected variants to judge how well the gene tolerates losing a copy. Missense variants: 587 observed, 561.36 expected, observed/expected ratio (o/e) 1.05, 90% interval 0.98 to 1.12. Synonymous variants: 258 observed, 251.61 expected, observed/expected ratio (o/e) 1.03, 90% interval 0.93 to 1.14.
Homologues: Orthologues: chimpanzee OXER1 (99% identical), macaque OXER1 (96% identical), dog OXER1 (76% identical), zebrafish hcar1-3 (33% identical), zebrafish hcar1-4 (26% identical). Paralogues in human: HCAR2 (31% identical), HCAR3 (30% identical), HCAR1 (30% identical), GPR31 (25% identical), P2RY2 (21% identical), P2RY1 (19% identical), P2RY4 (19% identical), OXGR1 (18% identical), P2RY6 (18% identical), SUCNR1 (17% identical), FFAR2 (17% identical), FFAR1 (16% identical), and 3 more.
Diseases named in the same sentence as OXER1 in open-access papers:
OXER1 is named in the same sentence as 15 diseases in open-access papers, as found by Europe PMC text mining. Sharing a sentence is not in itself a finding about the gene and the disease. The quoted sentences say what the papers report.
prostate carcinoma (8 papers, 2015 to 2024). A carcinoma that arises from epithelial cells of the prostate gland. "Both prostate cancer-derived cell lines and prostate cancer tissue from patients contain high levels of OXER1 at both mRNA and protein levels." (PMID 34831222, 2021). "Among the many actions of OXER1, the most relevant are the stimulation of steroidogenesis, cell proliferation and survival of prostate cancer cells, and inflammatory response." (PMID 33799482, 2021). "In fact, a meticulous analysis of 43 paired tumor/normal prostate cancer cases from TCGA revealed that OXER1 transcripts are lower in tumor than in normal tissue, pointing out that epigenetic elements might also be implicated in the expression of OXER1 in prostate cancer." (PMID 28290516, 2017). "In the present work we characterized the GPCR oxoeicosanoid receptor 1 (OXER1), as a specific membrane receptor that mediates rapid effects of androgens in prostate cancer cells." (PMID 28290516, 2017). "In this section, we try to establish further clinicopathological evidence about the expression and clinical significance of OXER1 in clinical specimens of prostate cancer." (PMID 28290516, 2017). "Indeed, OXER1 mediates cell proliferation, survival-promoting effects, and inhibition of cell apoptosis in prostate cancer cells, as well as adhesion, migration and invasion through its major signaling pathways involving p38α, PI3K/Akt and FAK." (PMID 34831222, 2021). "OXER1 has been reported to be upregulated in both prostate cancer cells as well as tumor tissues." (PMID 32961854, 2020). "Additionally, this interaction between androgen and OXER1, which is an arachidonic acid metabolite receptor expressed in prostate cancer, provides a novel link between steroid and lipid actions and renders OXER1 as new player in the disease." (PMID 28290516, 2017). "Hence, OXER1 could be a good target for inflammatory diseases, as well as for prostate cancer, since it is involved in the inhibition of prostate cancer cell apoptosis." (PMID 33799482, 2021). "However, in prostate cancer (PC), OXER1 transcripts are lower in tumor than in normal tissue, pointing out that epigenetic elements may also need to be considered in the expression of OXER1 in PC47." (PMID 33311444, 2020). "In fact, OXER1 expression parallels that of membrane androgen binding in prostate cancer cell lines and tumor specimens, while in silico docking simulation of OXER1 showed that testosterone could bind to OXER1 within the same grove as 5-OxoETE, the natural ligand of OXER1." (PMID 28290516, 2017). "Oxoeicosanoid receptor 1 (OXER1) is a membrane receptor for the arachidonic acid metabolite 5-oxoeicosatetraenoic acid (5-oxoETE) and serves as a binding site for testosterone in prostate cancer cells." (PMID 30100876, 2018). "Comparison of OXER1 and testosterone-BSA staining revealed a parallel increase of staining intensity between the two parameters in prostate cancer, further suggesting that OXER1 might be a membrane androgen binding protein." (PMID 28290516, 2017). "In addition, membrane staining for OXER1 has been found to be significantly increased in prostate cancerous tissues compared to non-cancerous ones, supporting OXER1’s role in prostate cancer cell growth and metastasis." (PMID 34831222, 2021). "However, OXER1 protein expression in prostate cancer specimens did not match tumor mRNA content." (PMID 28290516, 2017).
breast carcinoma (7 papers, 2017 to 2024). "OXER1 was involved in the rapid effects of androgens on prostate and breast cancer cells migration by inducing actin polymerization." (PMID 37991884, 2024). "OXER1 is highly expressed in inflammatory cells and many normal and cancer tissues and cells, including prostate and breast cancer, promoting cancer cell survival." (PMID 38202807, 2023). "Most of these roles are related to the immune system, but OXER1 is also essential in promoting survival, apoptosis inhibition, and infiltration of inflammatory cells in prostate and breast cancers." (PMID 36835177, 2023). "OXER1 promotes the migration of several cancer cell lines, including the T-47D breast cancer cell line." (PMID 37435447, 2022). "In agreement, inhibition of 5-oxo-ETE production by blocking 12-LOX and 5-LOX results in reduced proliferation and induced cytotoxicity and apoptosis, further supporting OXER1 role in breast cancer." (PMID 34831222, 2021). "We examined the expression of OXER1 both at mRNA and protein level in different cell lines of prostate (DU-145 and LNCaP) and breast cancer (T47D and SKBR3)." (PMID 28290516, 2017). "Interestingly, the role of OXER1/5-oxo-ETE is two-way, as tumor cells’ OXER1 activation by macrophages in DU-145 prostate and T47D breast cancer cells, on which OXER1 has been previously identified, induces actin cytoskeletal changes and migration." (PMID 38202807, 2023). "Finally, we report that 5-oxo-ETE, through OXER1, can attract macrophages to the tumor site while tumor cells’ OXER1 activation in DU-145 prostate and T47D breast cancer cells, by macrophages, induces actin cytoskeletal changes and increases their migration." (PMID 38202807, 2023). "OXER1 may also serve as a molecular marker in ERα-positive/HER2-negative breast cancers of adolescents and young adults." (PMID 37435447, 2022). "Indeed, OXER1 role in malignant cell growth was firstly reported in MDA-MB-231 and MCF-7 breast cancer cell lines, which express high levels of OXER1 protein." (PMID 34831222, 2021). "The levels of OXER1 mRNA are significantly lower in ER+ compared to ER- mammary tumors." (PMID 33311444, 2020). "In addition, since rapid androgen actions have been reported in classical AR-lacking breast cancer models and membrane androgen binding sites have been observed in breast carcinoma cells, OXER1 has been recently proposed as a potential drug target in breast cancer." (PMID 34831222, 2021). "OXER1 is a G protein-coupled receptor activated by 5-oxoeicosatretraenoic acid (5-oxo-ETE), which is produced by 5-lipoxygenase, resulting in increased breast cancer cell proliferation." (PMID 37435447, 2022). "Although the expression of OXER1 has not been thoroughly examined in breast cancer tissues, recent RNA-sequence analysis demonstrated that OXER1 expression is higher in ERα-negative breast cancers than in ERα-positive breast cancers." (PMID 37435447, 2022). "Thus, we evaluated the expression levels of OXER1 and RACK1 transcripts in estrogen-receptor-positive (ER+) and estrogen-receptor-negative (ER−) mammary tumors using the RNA-sequencing data available in the TCGA database." (PMID 33311444, 2020).
asthma (2 papers, 2023 to 2026). "Further evidence that the OXER1 gene is associated with the development of asthma may provide a new target for asthma treatment." (PMID 41573111, 2026). "Five druggable genes significantly associated with asthma were identified in whole blood (IRF1, OXER1, PSMA4, UNC13D, and HLA‐DRB1) and one in lung tissue (CD226)." (PMID 41573111, 2026). "OXE receptor, encoded by the OXER1 gene, may be a target for the treatment of asthma, for which an animal study was carried out in the selection of an OXE receptor antagonist." (PMID 41573111, 2026). "Targeting this pathway (e.g., the OXER1 antagonist S‐005) may be particularly indicated in patients with severe asthma with elevated levels of 5‐oxo‐ETE." (PMID 41573111, 2026). "IRF1 (PPH4/PPH3 + PPH4 = 0.975), OXER1(PPH4/PPH3 + PPH4 = 0.967), PSMA4(PPH4/PPH3 + PPH4 = 0.972), UNC13D (PPH4/PPH3 + PPH4 = 0.989) and HLA‐DRB1(PPH4/PPH3 + PPH4 = 0.948) expression had significant colocalization associations with asthma." (PMID 41573111, 2026). "OXER1 is expressed in human leucocytes (lymphocytes, monocytes, neutrophils, and eosinophils) and various tissues, while a primary role of 5-oxo-ETE in asthma has been found, with specific OXER1 antagonists currently investigated as a potential novel treatment." (PMID 38202807, 2023).
oral cancers (2 papers, 2020 to 2023). "Since HPV is found to play a role in the onset and progression of HN as well as oral cancers, we suggest a link between OXER1 expression and HN as well as oral cancers." (PMID 32961854, 2020). "So far, no direct studies have investigated the role of OXER1 in HNSCC, but upregulation of the OXER1 gene was reported in HPV+ oropharyngeal and oral cancers." (PMID 36835177, 2023).
airway hyperresponsiveness (1 paper, 2026). "oXER1 activates UNC13D‐dependent degranulation via calcium signaling, while UNC13D deficiency attenuates airway hyperresponsiveness." (PMID 41573111, 2026).
lung carcinoma (1 paper, 2026). "OXER1 was previously reported to be highly expressed in leukocytes, macrophages, monocytes and cancer cells, which and it has been shown that 5‐LOX is directly involved in lung cancer progression." (PMID 41573111, 2026).
metastatic prostate carcinoma (1 paper, 2017). A carcinoma that arises from the prostate gland and has spread to other anatomic sites. "In contrast to metastatic prostate cancer, data from TCGA regarding primary prostate adenocarcinomas showed a great disparity in OXER1 levels of expression." (PMID 28290516, 2017).
monocytic leukemia (1 paper, 2023). "Furthermore, when THP-1, a monocytic leukemia cell line, was treated with different doses of LPS, OXER1 expression was equally increased in a dose-dependent manner." (PMID 38202807, 2023).
cancer (7 papers, 2017 to 2026). A tumor composed of atypical neoplastic, often pleomorphic cells that invade other tissues. "The use of various blockers of 5‐LOX and OXER1 has led to improved efficacy in the treatment of various cancers." (PMID 41573111, 2026). "By contrast, expression levels of OXER1 mRNA in the most common EOC (represented here by OVCAR-3 cells) were similar to that in non-cancer epithelial cells (HOSEpiC)." (PMID 39464509, 2024). "We have previously reported that 5-oxo-ETE triggers actin cytoskeleton rearrangements in prostate DU145 cancer cells, which highly express OXER1 but lack AR, leading to an increase in formation of stress fibers and an increased migratory capacity." (PMID 38202807, 2023). "In this respect, specific OXER1 antagonists modifying actin cytoskeleton and cell migration are prominent candidates as novel anti-cancer agents." (PMID 38202807, 2023). "5-oxo-ETE produced within the tumor microenvironment (TME) can support OXER1-mediated cancer cell growth and promote further infiltration of inflammatory cells." (PMID 34831222, 2021). "However, the GEPIA database showed that tumours express markedly lower levels of OXER1 mRNA than normal tissues (p < 0.05), and that expression decreases as the cancer stage increases." (PMID 39464509, 2024). "Taking into account these findings and that it has been previously reported that macrophages produce 5-LOX products, including 5-HETE, the precursor of 5-oxo-ETE, the involvement of 5-oxo-ETE/OXER1 on the migration of cancer cells in the presence of macrophages was also explored." (PMID 38202807, 2023). "Finally, we have shown that OXER1 is up-regulated by its ligand 5-oxo-ETE at the leading edge of the wound in human cancer epithelial cells (prostate, breast, and hepatocellular), mimicking the activation/migration phase of healing." (PMID 38202807, 2023). "Literature data confirmed that OXER1 is highly expressed in cancer cells and tissues, including prostate and breast, where it has been observed to mediate survival-promoting effects and inhibition of cell apoptosis, when activated by its endogenous ligand 5-oxo-ETE." (PMID 34831222, 2021). "In the present study we investigate the expression and role of OXER1 in WBCs, THP-1 monocytes, and THP-1 derived macrophages, as well as its possible role in the interaction between macrophages and cancer cells (DU-145 and T47D)." (PMID 38202807, 2023). "As OXER1 inhibits some of the major signaling pathways (FAK, PI3K/Akt, p38α) controlling cell growth, is likely to represent a new mediator of the anti-proliferative and anti-migratory actions exerted by androgens in cancer cells." (PMID 33311444, 2020).
tumor (5 papers, 2017 to 2024). "We found differences in expression of ZIP9 and OXER1 between different OC subtypes, as well as between patient tumour and normal tissues." (PMID 39464509, 2024). "In conclusion, our data position OXER1 as a prominent tumor-inflammatory component, promoting both macrophage migration toward the tumor mass and tumor cell migration through the TME, possibly facilitated by the M2 macrophage-secreted MMPs." (PMID 38202807, 2023). "This is exactly what we observe in MCF7 cells where the anti-tumor action of testosterone-BSA is OXER1 and RACK1 dependent." (PMID 33311444, 2020). "Here, we propose a third mechanism, namely the interaction of OXER1 with circulating androgen, eliciting rapid, membrane initiated, effects in tumor cells, regulating their fate." (PMID 28290516, 2017). "However, it cannot be excluded that another ALOX5 metabolite is also equally involved in stimulating 5-oxo-ETE synthesis by tumor cells, resulting in OXER1-mediated enhanced migration." (PMID 38202807, 2023). "We have further constructed a tissue microarray with paired normal and tumor prostate tissue from a limited number of patients and stained it for OXER1 and membrane androgen binding sites, in order to provide a proof of principle of OXER1-Testosterone-BSA membrane binding." (PMID 28290516, 2017). "We performed further quantitative correlation studies between the expression levels of OXER1/RACK1 mRNAs and the following parameters: age of diagnosis, ER-positivity, PR-positivity, HER2-positivity, incidence of relapse (new tumor event) and tumor stage." (PMID 33311444, 2020).
OXER1 also shares sentences with these, for which no sentence is quoted: adrenocortical cancer (1 paper); coronary artery disease (1); diabetes (1); Obesity (1); prostate adenocarcinoma (1).